PHF14 (PHD finger protein 14)
Diseases named in the same sentence as PHF14 in open-access papers (continued):
Sharing a sentence is not in itself a finding about the gene and the disease.
glioma (2 papers, 2019 to 2023). A benign or malignant brain and spinal cord tumor that arises from glial cells (astrocytes, oligodendrocytes, ependymal cells). "To better understand the underlying mechanism of PHF14’s effect on glioma cells, we performed RNA sequencing analysis upon U251 negative control and shPHF14 transfected cells." (PMID 31798343, 2019). "The upregulation of PHF14 is really closely associated to the malignant nature of glioma, especially in GBM." (PMID 31798343, 2019). "Considering the upregulation of PHF14 in glioma, especially in GBM, we presumed it to be a transcription regulator with repressing and/or activating roles at different genes during the tumorigenesis of GBM." (PMID 31798343, 2019). "While our study also observed the significant effects of IWR-1 on cell viability in U251 glioma cells, PHF14 depleted cells showed greater resistance to IWR-1 sensitization." (PMID 31798343, 2019). "In vitro assays revealed that silencing expression of PHF14 in glioma cells inhibited migration, invasiveness and proliferation and promoted cell apoptosis." (PMID 31798343, 2019). "The mRNA expression level of PHF14 was significantly higher in iso-citrate dehydrogenase (IDH) wild-type low-grade gliomas (LGG)." (PMID 31798343, 2019). "Our results showed the Wnt signaling pathway to be inhibited by silencing expression of PHF14, suggesting PHF14 involvement in the pathogenesis of glioma via Wnt/β-catenin signaling pathway." (PMID 31798343, 2019). "Our data provide a new insight into the biological significance of PHF14 in glioma and its potential application in therapy and diagnosis." (PMID 31798343, 2019). "By performing immunohistochemistry on three tissue microarrays, we found a positive correlation between glioma grade and the staining intensity of PHF14." (PMID 31798343, 2019). "The findings suggested an upregulation of PHF14 expression in glioma." (PMID 37007943, 2023). "Our results showed that the expression of PHF14 was upregulated in glioma, especially in GBM." (PMID 31798343, 2019). "Overexpression of PHF14 translated to poor prognosis in glioma patients." (PMID 31798343, 2019). "PHF14 could be a novel key molecule in the pathogenesis of gliomas and should be further explored as a putative therapeutic target." (PMID 31798343, 2019). "In summary, PHF14 expression correlates with glioma grades and patients’ survival." (PMID 31798343, 2019). "The mRNA expression level of PHF14 significantly increases with increasing WHO glioma grade." (PMID 31798343, 2019). "Additionally, silencing PHF14 gene could effectively suppress the migration, invasion and proliferation of glioma cells, and promote cell apoptosis." (PMID 37007943, 2023). "However, the role of PHF14 remains to be explored in glioma." (PMID 31798343, 2019). "To study the biological function of PHF14 in glioma cells, we used lentiviral short hairpin RNA to construct the stable PHF14-silenced U251, U87MG and A172 glioma cell lines." (PMID 31798343, 2019).
hepatocellular carcinoma (2 papers, 2017 to 2024). A malignant tumor that arises from hepatocytes. "PHD finger proteins, particularly PHF14 and PHF19, exhibit a profound capacity to regulate immune cell infiltration and checkpoint gene expression within tumors, thereby influencing the immune landscape of various cancers, including hepatocellular carcinoma." (PMID 38813086, 2024).
renal fibrosis (2 papers, 2017 to 2020). A final common manifestation of a wide variety of chronic kidney diseases characterized by glomerulosclerosis and tubulointerstitial fibrosis. "Compared with wild-type mice, PHF14-null mice showed more severe renal fibrosis after pro-fibrotic stimuli." (PMID 28045076, 2017). "PHF14 inhibits renal fibrosis after kidney injury induced by folic acid." (PMID 32596345, 2020). "The aim of this study was to investigate PHF14 function in renal fibrosis." (PMID 28045076, 2017). "PHF14 deletion in mice promotes ECM production and renal fibrosis after folic acid administration." (PMID 28045076, 2017).
acute kidney injury (1 paper, 2017). Sudden and sustained deterioration of the kidney function characterized by decreased glomerular filtration rate, increased serum creatinine or oliguria. "Therefore, the primary objectives of this study were to investigate the expression profile of PHF14 in the scenario of TIF following acute kidney injury induced by folic acid, to illuminate the role of PHF14 in renal TIF, and to examine the interaction between PHF14 and TGF-β signaling." (PMID 28045076, 2017).
adenovirus infection (1 paper, 2017). "By phf14-3-FLAG adenovirus infection, exogenous PHF14 was introduced into NRK-49F cells." (PMID 28045076, 2017). "On the other hand, α-SMA and collagen I expression induced by TGF-β was not affected by overexpression of PHF14 with phf14-3-FLAG adenovirus infection (data not shown), suggesting that the endogenous expression levels of PHF14 were enough to maintain the normal physiological function." (PMID 28045076, 2017).
asthma (1 paper, 2018). "In the AA childhood asthma GWAS, no SNPs reached the level of genome-wide significance, however, regions of interest were identified in FLJ12825 (p = 1.75 × 10− 7) and PHF14 (p = 4.94 × 10− 7)." (PMID 30373671, 2018).
craniosynostosis (1 paper, 2017). Craniosynostosis is defined as the premature fusion of one or more cranial sutures leading to secondary distortion of skull shape resulting in skull deformities with a variable presentation. "In particular, when persistent pulmonary hypertension is coupled with craniosynostosis and dysmorphic features, involvement of TWIST1 and PHF14 should be considered." (PMID 28814329, 2017).
developmental delay (1 paper, 2024). "Additionally, PHF14 has also been linked to ASD, and two patients with single nucleotide or nonsense variants of PHF14 presented neurological features such as speech impairments, developmental delay, and ID." (PMID 39766920, 2024).
esophageal carcinoma (1 paper, 2023). A primary or metastatic malignant neoplasm involving the esophagus. "However, higher levels of PHF14 expression were observed in adjacent normal tissues than that in esophageal carcinoma (ESCA) and kidney chromophobe (KICH) tumor tissues (p < 0.01)." (PMID 37007943, 2023).
Hypertension (1 paper, 2016). The presence of chronic increased pressure in the systemic arterial system. "Marker rs218966 in gene PHF14 and rs9836027 in MAP4 significantly associated with hypertension; additionally, rare variants in SNUPN significantly associated with systolic blood pressure." (PMID 26866982, 2016).
Immunodeficiency (1 paper, 2022). Failure of the immune system to protect the body adequately from infection, due to the absence or insufficiency of some component process or substance. "Point mutations, deletion or chromosomal translocations in the PHF14 plant homeodomain family fingers are found in a wide range of pathologies, including cancer, mental retardation and immunodeficiency." (PMID 36359362, 2022).
lentivirus infection (1 paper, 2022). Virus diseases caused by the Lentivirus genus. "As these splice site losses resulted in disrupted PHF14 function, we used lentivirus infection to introduce wild type full length PHF14 into the primary neurocytoma cells." (PMID 36359362, 2022).
neuroblastoma (1 paper, 2022). Neuroblastoma (NB) is the most common solid, extracranial childhood tumor. "As no neurocytoma cell lines exist, we used neuroblastoma SHSY-5Y cells as a surrogate model to examine effects of PHF14 loss on anchorage-independent cell growth, an indicator of tumor cell aggressiveness and metastatic potential." (PMID 36359362, 2022). "Consistent with what we observed previously in the PHF14 knockdown neuroblastoma SHSY-5Y cells, the primary neurocytoma cells exhibited greater sensitivity to Sunitinib treatment (5 μM, 0.1 ± 0.01 vs. 1.0 ± 0.04, p < 0.005) when compared to the MAPK/ERK or AMPK/AKT inhibitors MEK-162 and Metformin." (PMID 36359362, 2022). "Additionally, we demonstrated that PHF14 depletion resulted in upregulation of platelet derived growth factor receptor-alpha (PDGFRα) mRNA and protein in neuroblastoma SHSY-5Y cells and led to increased sensitivity to treatment with the PDGFR inhibitor Sunitinib." (PMID 36359362, 2022).
neurocytomas (1 paper, 2022). "Whole exome sequencing in 21 neurocytoma tumor tissues identified somatic mutations in the plant homeodomain finger protein 14 (PHF14) in 3/21 (14%) tumors." (PMID 36359362, 2022). "Multiple somatic mutations in the plant homeodomain finger protein 14 (PHF14) were identified in 3/21 (14%) neurocytomas." (PMID 36359362, 2022). "Altogether our studies demonstrate a significant mutation frequency of PHF14 in neurocytomas and predict a favorable response to Sunitinib treatment in patients with neurocytomas harboring a PHF14 defect." (PMID 36359362, 2022). "Herein we describe mutations in PHF14 gene in a series of neurocytomas." (PMID 36359362, 2022). "Disruptive PHF14 mutations were found in 3 of 21 (14%) neurocytoma tissues by WES." (PMID 36359362, 2022). "Interestingly, whole exome sequencing of this neurocytoma revealed 4 variants in PHF14 at intronic regions c.901-3T>G (NM_014660 intron 3), c.1980+1G>C/+4A>T (intron 9), and c.2654+1G>A (intron 13)." (PMID 36359362, 2022). "Furthermore, in a neurocytoma primary culture harboring splicing loss PHF14 mutations, overexpression of wild-type PHF14 and sunitinib treatment inhibited cell proliferation." (PMID 36359362, 2022). "Altogether our studies identified mutations of PHF14 in 14% of neurocytomas, demonstrate it can serve as an alternative pathway for certain cancerous behavior, and suggest a potential role for Sunitinib treatment in some patients with residual/recurrent neurocytoma." (PMID 36359362, 2022). "In summary, we have identified a genetic variant of PHF14 in 14% of neurocytomas using WES and demonstrated that loss of PHF14 function resulted in increased cell proliferation in several cell lines and in a neurocytoma primary culture." (PMID 36359362, 2022). "Altogether our studies support a putative tumor proliferation inhibition role of PHF14 in some neurocytomas, and suggest that Sunitinib could be a feasible treatment choice for some patients with residual/recurrent neurocytoma." (PMID 36359362, 2022). "Our additional studies of PHF14 function in several cell lines corroborated by a single neurocytoma primary culture point to a putative regulatory role of PHF14 in modulating cell proliferation, PDGFRα expression and sensitivity to the anti-proliferative effect of the PDGFR inhibitor Sunitinib." (PMID 36359362, 2022). "Our findings suggest that Sunitinib could be a feasible treatment choice for some neurocytoma patients that exhibit PHF14 defects." (PMID 36359362, 2022). "Our studies indicate that lack of PHF14 may be a predictive biomarker for Sunitinib treatment in neurocytomas." (PMID 36359362, 2022).
osteosarcoma (1 paper, 2025). A usually aggressive malignant bone-forming mesenchymal neoplasm, predominantly affecting adolescents and young adults. "In this study, mouse osteosarcoma K7M2 cells were analyzed and several highly immunogenic neoantigens (Golgb1 and Phf14) were identified." (PMID 39742319, 2025).
ovarian serous cystadenocarcinoma (1 paper, 2023). A malignant serous cystic epithelial neoplasm arising from the ovary. "However, PHF14 expression levels was lower in ovarian serous cystadenocarcinoma (OV) and thyroid carcinoma (THCA) tumor tissues than in adjacent normal tissues (p < 0.001)." (PMID 37007943, 2023).
pancreatic adenocarcinoma (1 paper, 2023). "It was also observed that PHF14 expression levels was not statistically significant between the adjacent normal tissues and the pancreatic adenocarcinoma (PAAD) and uterine corpus endometrial carcinoma (UCEC) tumor tissues." (PMID 37007943, 2023).
paraganglioma (1 paper, 2023). A benign or malignant neoplasm arising from paraganglia located along the sympathetic or parasympathetic nerves. "Moreover, PHF14 expression levels in kidney chromophobe (KICH) and pheochromocytoma and paraganglioma (PCPG) tumor tissues were also not distinctly different from those of the adjacent normal tissues (ns: p > 0.05)." (PMID 37007943, 2023).
pulmonary hypertension (1 paper, 2017). Increased pressure within the pulmonary circulation due to lung or heart disorder. "We are not aware of any prior description of patients with therapy-refractory pulmonary hypertension in conjunction with a deletion of chromosome 7 involving TWIST1 and PHF14, and believe this to be an important differential diagnosis in neonates with this presentation." (PMID 28814329, 2017).
cancer (14 papers, 2013 to 2024). A tumor composed of atypical neoplastic, often pleomorphic cells that invade other tissues. "PHF14 possibly exerts an effect on the survival status of patients by modifying the immune cell infiltration in the tumor microenvironment, such as cancer-associated fibroblasts, which requires further investigation." (PMID 37007943, 2023). "Levels of cancer-associated fibroblasts (CAFs) infiltration in various cancer types were also observed to correlate with PHF14 expression." (PMID 37007943, 2023). "In this report, we investigated the association between PHF14 and cell cycle arrest in cancer cells." (PMID 31040906, 2019). "Abnormal expression of PHF14 has been identified in various cancers and is known to be implicated in the pathogenesis of tumors." (PMID 31798343, 2019). "Recently, it was appeared in a possible correlation between DHHC-type protein acyltransferase, DHHC3 and PHF14 as depletion of DHHC down-regulated PHF14 in cancer but underlying mechanism remains obscure." (PMID 31040906, 2019). "Therefore, expression level of PHF14 is associated with status of protein translation in cancer cells." (PMID 31040906, 2019). "Several other studies have implicated PHF14 in diseases including cancers." (PMID 28160558, 2017). "Generally epigenetic modifiers regulate gene expression by the assembly of relevant interacting partners, thus, contradict outcome of PHF14 depletion in different cancer cells might be associated with its functional binding partners and environmental stress may affect the complex formation." (PMID 31040906, 2019). "Genes shared by cluster A and D represent a link between chromatin organization and cancer hallmark processes, involving FOXA1, ESRI, PHF14 and the ATPase proteasome subunits, PSMC5 and PSMC4." (PMID 38625038, 2024). "The cancer cases included in this study were sorted into a low PHF14 expression group and a high PHF14 expression group based on PHF14 expression." (PMID 37007943, 2023). "It is further revealed that amplification or mutation is the most common type of alteration of PHF14 in most types of tumors, and the alteration of PHF14 is associated with poor prognosis of OS, DSS and PFS in cancer patients through the cBioPortal tool." (PMID 37007943, 2023). "Using HPA, GTEx, and FANTOM5 (Functional Annotation of Mammalian Genomes) datasets, PHF14 was shown to be enriched in thymus and ovary, and highly expressed in cerebral cortex and cerebellum among other cancers." (PMID 37007943, 2023). "Based on existing datasets from the Cancer Genome Atlas (TCGA) and the Gene Expression Omnibus (GEO), we performed a systematic analysis of the oncogenic role of the PHF14 gene in 33 human cancers." (PMID 37007943, 2023). "In conclusion, our pan-cancer research shows that the expression level of PHF14 is closely related to the carcinogenesis and prognosis of certain tumors, which needs to be further verified by more experiments and more in-depth mechanism exploration." (PMID 37007943, 2023). "In many cancer cells, these genes are controlled by epigenetic tools such as DNA methylation or histone demethylation, indicating the potential role of PHF14 as an epigenetic regulator in early response stage of cells to hypoxic stress." (PMID 31040906, 2019). "Analysis of two cancer datasets clearly indicated that gene expression of PHF14 was positively correlated with expression of those eukaryotic translation initiation factors." (PMID 31040906, 2019). "While a potential role of PHF14 in cancer was studied in context of epigenetic regulator or transcription factor, little is still known about upstream regulators of PHF14." (PMID 31040906, 2019). "Our findings have thus unveiled the novel exploitable role of hypoxia-sensitive PHF14 by cancer cells to adapt to the stressful oxygen-depleted tumor microenvironment." (PMID 31040906, 2019).